IKZF3 (IKAROS family zinc finger 3)
Diseases named in the same sentence as IKZF3 in open-access papers (continued):
Sharing a sentence is not in itself a finding about the gene and the disease.
gastric cancer (2 papers, 2024 to 2025). A primary or metastatic malignant neoplasm involving the stomach. "Moreover, IKZF3 amplification is significantly associated with vessel invasion in early gastric cancer, this indicate IKZF3 amplification could potentially be a clue to distinguish between endoscopic submucosal dissection (ESD) and gastrectomy cases." (PMID 39052108, 2024). "IKZF3 amplification was detected in 6.9% (28/404) of all GC patients, with higher rates in intestinal-type gastric cancer (IGC) (11.22%, 22/196) compared to other types (2.88%, 6/208)." (PMID 39052108, 2024). "However, IKZF3 amplification and clinical significance in gastric cancers (GCs) remain unexplored." (PMID 39052108, 2024).
hypothyroidism (2 papers, 2023 to 2024). Abnormally low levels of thyroid hormone. "A common genetic etiology was proposed between hypothyroidism and OLP81 and our study supports this, indicating variation at nine loci (IFIH1, LPP, CEP43, TNRC18, C12orf42, TNFSF11, ST3GAL6, IL2RA, and IKZF3) that are strongly associated with both LP and autoimmune hypothyroidism." (PMID 38776927, 2024).
immunodeficiency 84 (2 papers, 2022 to 2025). "Mutation in IKZF3 is linked to immunodeficiency-84, which is an autosomal dominant primary immunologic disease associated with low levels of B cells and impaired early B-cell development." (PMID 40406108, 2025).
liver fibrosis (2 papers, 2022 to 2023). "IRF8, NR4A2, IKZF3, and REL may be involved in the transcriptional regulation of NK cells in liver fibrosis." (PMID 35903097, 2022).
acute sinusitis (1 paper, 2023). "These 56 phenotypes include infectious and inflammatory disorders of the upper respiratory tract that were not included in our definition of IURD: acute sinusitis (9p24.1 near IL33 and 17q21.1 near IKZF3) and acute respiratory infections (5q22.1 near TSLP/WDR and 9p24.1 near IL33)." (PMID 36653354, 2023).
adult onset asthma (1 paper, 2011). "In this study, we aimed to evaluate the association of polymorphisms in ORMDL3, GSDMB, ZPBP2 and IKZF3 and adult-onset asthma in a Chinese Han population." (PMID 21985515, 2011).
Arthritis (1 paper, 2018). Inflammation of a joint. "Conceiveably, our observations with regard to PADI4 and IKZF3 could be interpreted as evidence that putatively common causal SNPs augment gene expression in CD4+ T cells uniquely under the particular biologic and/or environmental circumstances of early arthritis." (PMID 29193869, 2018).
bladder (1 paper, 2022). "However, the mechanism of action in bladder cancers of IKZF3 and density lipoprotein-binding protein (HDLbp), which has not been reported, may be a new prospective therapeutic target for immunotherapy in bladder patients and is worthy of further exploration." (PMID 36211821, 2022).
Bladder Urothelial Carcinoma (1 paper, 2022). "Since HPV infection is suspected to contribute to the emergence of other cancer types (Bladder Urothelial Carcinoma (BLCA), HNSC, Colon adenocarcinoma (COAD), Prostate Adenocarcinoma (PRAD)), an HPV-associated pan cancer analysis of IKZF3, FOXP3, and JAK3 was performed." (PMID 35719936, 2022).
cervical cancer (1 paper, 2023). A primary or metastatic malignant neoplasm involving the cervix. "Recently, studies have explored the relationships between IKZF3 and hypoxia-immunity in cervical cancer, which may be beneficial to the development of novel prognostic biomarkers and therapeutic strategies for cervical cancer." (PMID 36837559, 2023).
childhood asthma (1 paper, 2023). "Previous studies have reported that the 17q21 locus alleles in genes GSDMA, GSDMB, IKZF3, ZPBP2, and ORMDL3 are associated with increased risk and severity of childhood asthma and increased number of early wheezing illnesses." (PMID 36967681, 2023).
colitis (1 paper, 2025). Inflammation of the colon. "Additionally, the cytotoxic potential of effector-like IELs has been shown in DSS-induced colitis, where tissue damage was reduced in Ikzf3 KO mice with decreased amounts of effector-like IELs." (PMID 40837586, 2025).
diffuse large B-cell lymphoma (1 paper, 2020). "CC-122 binds CRL4CRBN E3 ligase to induce the degradation of IKZF1 and IKZF3 in MM cells, diffuse large B-cell lymphoma (DLBCL) cells and xenograft mouse models established from DLBCL cells." (PMID 31938543, 2020).
esophagitis (1 paper, 2025). An acute or chronic inflammatory disease affecting the esophageal wall. "Additionally, two SSc patients carried the chr17:37922552 T/C variant in the IKZF3 gene, also classified as a VUS, and associated with cutaneous, articular, and vascular impairment, as well as ILD and esophagitis (χ2 > 16, p < 0.0001)." (PMID 41283471, 2025).
experimental autoimmune encephalomyelitis (1 paper, 2020). An autoimmune demyelinating disease of the central nervous system that is produced experimentally in animals by the injection of homogenized brain or spinal cord in Freund's adjuvant. "The expression of IKZF3 and IL-10 in nonpathogenic Th17 cells with a reduced capacity to drive experimental autoimmune encephalomyelitis has been previously noted." (PMID 32321757, 2020).
lipid metabolism disorders (1 paper, 2024). "Moreover, genome‐wide association studies (GWASs) have shown that IKZF3 is associated with lipid metabolism disorders." (PMID 38193570, 2024).
metastasis (1 paper, 2024). The spread or migration of cancer cells from one part of the body (where they first appeared) to another. "Given the strong correlation between IKZF3 amplification and intestinal-type GC, we then analyzed its association with lymph node metastasis and vessel invasion in early-stage GC patients (Tis + T1a + T1b)." (PMID 39052108, 2024).
monoclonal gammopathy of undetermined significance (1 paper, 2015). "In contrast, we did not observe significant change in the expression of either IKZF1 or IKZF3 genes during the progression from normal to monoclonal gammopathy of undetermined significance and SMM to newly diagnosed MM." (PMID 26430725, 2015).
pancreatic cancer (1 paper, 2023). "According to our understanding, no previous studies have explored whether IKZF3 and ITGA8 are engaged in the initiation and progression of pancreatic cancer." (PMID 36837559, 2023).
sarcoidosis (1 paper, 2022). Sarcoidosis is a multisystemic disorder of unknown cause characterized by the formation of immune granulomas in involved organs. "In a prior gene co-expression analyses of peripheral blood and cutaneous lesions we noted that transcription factors, such as ETS1, IKZF3, LEF1, MYC, RORA, and SPI1 (PU.1), may be central players in aberrant processes associated with sarcoidosis." (PMID 36311769, 2022).
T-cell neoplasms (1 paper, 2022). "The GATA-3 target genes shared across the continuum of T-cell neoplasms are therapeutically relevant, including immunomodulatory drugs (IMiDs) that lead to IKZF3 degradation, and the CCR4 specific monoclonal antibody mogamulizumab." (PMID 36329027, 2022).
triple-negative breast carcinoma (1 paper, 2020). An invasive breast carcinoma which is negative for expression of estrogen receptor (ER), progesterone receptor (PR), and human epidermal growth factor receptor 2 (HER2). "The same is true for BCL11B, IKZF3, and KLRC4, which have very recently been linked to a prognostic immunogenic signature of triple-negative breast cancers." (PMID 32605588, 2020).
vitamin D deficiency (1 paper, 2024). A nutritional condition produced by a deficiency of VITAMIN D in the diet, insufficient production of vitamin D in the skin, inadequate absorption of vitamin D from the diet, or abnormal conversion of vitamin D to its bioactive metabolites. "Vitamin D deficiency differentially regulated the expression levels of several Chr17q12-21.1-encoded genes, with lower expression of Ikzf3, Ormdl3, and Gsdma (all p = 0.0286)." (PMID 38567749, 2024).
tumor (34 papers, 2011 to 2025). "This signature consists of 5 genes (HOTAIR, PLK1, LAMA3, EDA2R, and IKZF3) that are closely linked to tumor development." (PMID 37904416, 2023). "This orally bioavailable compound selectively targets IKZF1 (Ikaros) and IKZF3 (Aiolos), causing tumor cell death upon their depletion from malignant B cells and T cell activation when depleted from the tumor microenvironment." (PMID 37669923, 2023). "IKZF3 expression in tumor cells was positively associated with increased drug sensitivity to Fluphenazine、Alectinib, and negatively associated with Irofulven." (PMID 36353107, 2022). "Univariate analysis suggests that pTNM stage, HER2 amplification, LN metastasis, IKZF3 amplification, tumor deposits, vessel invasion, and nerve invasion were significantly linked to DFS and OS in IGC patients." (PMID 39052108, 2024). "First, the use of TMA technique can underestimate or overestimate IKZF3 status due to tumor and microenvironment heterogeneity." (PMID 39052108, 2024). "In stages III-IV IGC patients, univariate analysis suggests that age, IKZF3 amplification, and tumor deposits exhibit correlation with both DFS and OS." (PMID 39052108, 2024). "Our results indicated significant overexpression of GALNT2, MTHFD1, FAM207A, KRT81, and IKZF3 in tumor tissues, consistent with our bioinformatics analysis." (PMID 38596689, 2024). "The HR < 1 downregulation of PTPN6 and IKZF3 is considered a tumor suppressor, while the HR > 1 upregulation of HDLBP and EMC1 is considered an oncogene." (PMID 36211821, 2022). "IKZF1 and IKZF3 are considered tumor suppressors and their inability to perform their functions are connected with tumor development." (PMID 29903986, 2018). "IMiDs have also been shown to modulate the immune system in addition to causing direct cytotoxicity of tumor cells through the regulation of IKZF1 and IKZF3 protein abundance." (PMID 28264055, 2017). "Additionally, IKZF3 promotes tumor progression, and its high expression in intestinal-type gastric cancer is linked to a poor prognosis." (PMID 40093905, 2025). "Its involvement in LUAD could be related to immune evasion mechanisms, where altered expression of IKZF3 affects the immune microenvironment’s ability to recognize and eliminate tumor cells." (PMID 38596689, 2024). "The functions of FOXP3, JAK3, and IKZF3 are widely researched in the field of tumor immunology." (PMID 35719936, 2022). "Furthermore, IKZF3 promotes GC tumor growth in xenograft models." (PMID 40761106, 2025). "Besides, univariate analysis of prognostic significance suggests that age, pTNM stage, Lauren classification, LN metastasis, IKZF3 amplification, tumor deposits, vessel invasion and nerve invasion were significantly associated with DFS and OS in all GC patients." (PMID 39052108, 2024). "Meanwhile, the expressions of IKZF3 and CD70 were significantly higher in tumor tissues than those in normal tissues." (PMID 40860241, 2025). "The mRNA expression of seven PRAN genes (CCL14, CPA3, CX3CR1, IKZF3, KIF21B, LINC00528, and SLC16A4) showed significant differences between normal and tumor samples in the advanced NSCLC cohort." (PMID 38728242, 2024). "In the multivariate analysis, IKZF3 amplification (P = 0.045, HR: 2.320 for DFS; P = 0.865, HR: 0.881 for OS) and tumor deposits (P = 0.007, HR: 1.286 for DFS; P = 0.26, HR: 1.25 for OS) were associated with DFS, but not with OS." (PMID 39052108, 2024). "In the multivariate analysis, IKZF3 amplification (P = 0.007, HR: 3.381 for DFS; P = 0.004, HR: 3.734 for OS) and tumor deposits (P < 0.001, HR: 1.334 for DFS; P = 0.003, HR: 2.519 for OS) were associated with DFS and OS." (PMID 39052108, 2024). "The mRNA expression of seven PRAN genes (CCL14, CPA3, CX3CR1, IKZF3, KIF21B, LINC00528, and SLC16A4) exhibited noticeable difference between normal and tumor in NSCLC." (PMID 38728242, 2024).
tumor (continued). "The multivariate four-factor model (tumour stage, age, CIITA, IKZF3) was validated in the MEL_TCGA independent validation data (n = 135, TCGA_VALID)." (PMID 35743743, 2022). "Multivariate analysis controlling for tumour stage and age highlights CIITA and IKZF3 as candidate prognostic biomarkers." (PMID 35743743, 2022). "A significant top-scoring model (tumour stage, age, CIITA, IKZF3, CD247, TENT5C; likelihood ratio test p = 2 × 10−7) was returned for the MEL_TCGA training set (n = 255, TCGA_TRAIN)." (PMID 35743743, 2022). "So far, three CRL4CRBN substrates have been identified that mediate the anti-tumor activity of IMiDs in hematologic malignancies, including the Ikaros family zinc finger proteins 1 and 3 (IKZF1 and IKZF3) and casein kinase 1 alpha (CK1α)." (PMID 34680233, 2021). "Depletion of these transcription factors in MM cell lines leads to inhibition of tumor cell growth, confirming the role of IMiD-mediated degradation of IKZF1 and IKZF3 on reducing myeloma cell proliferation." (PMID 28264055, 2017). "The anti-tumor effects induced by LEN are mediated through the modification of the target specificity of CRBN, an E3 enzyme responsible for ubiquitinating IKZF1 and IKZF3 in MM cells, as well as casein kinase 1 alpha (CK1α) in 5q-MDS." (PMID 38344143, 2023). "Moreover, among different tumor locations, Ikaros genes were expressed at the highest levels in regional lymph nodes, IKZF1 and IKZF3 were expressed at the lowest levels in distant metastases, and IKZF2, IKZF4, and IKZF5 were expressed at the lowest levels in the primary tumor." (PMID 36353107, 2022). "IKZF3 and ITGA8 were considerably more lowly expressed in the normal cell lines compared with the tumor cell lines." (PMID 36837559, 2023). "In the study of OPSCC, IKZF3 RNA was detected in HPV+ cell lines, and regardless of tumor cell expression pattern, the immune cell infiltration was significantly positive for IKZF3." (PMID 35719936, 2022). "We stratified basal tumours in Take and No Take groups and noted that the expression of ZNF831, IKZF3 and SP140 was lower in the Take compared with the No Take group (p < 0.05)." (PMID 28588211, 2017).
cancer (25 papers, 2011 to 2025). A tumor composed of atypical neoplastic, often pleomorphic cells that invade other tissues. "The Pearson coefficient index of every pair of Ikaros genes indicated that IKZF1 and IKZF3 were closely associated in various cancers, while IKZF3 and IKZF5 showed the weakest correlations." (PMID 36353107, 2022). "Among them, CUX1, IKZF3, and NR4A1 (highlighted in red in the figure) are well-documented cancer-associated factors." (PMID 40923764, 2025). "The prognostic significance of IKZF3 requires more test-proof evidences in the future, which offers perspective on a potential role of IKZF3 as a promising druggable target for GC as well as other carcinomas." (PMID 39052108, 2024). "Pan-cancer analysis identified IKZF3, FOXP3, and JAK3 had a similar distribution and effects in HPV-associated HNSC." (PMID 35719936, 2022). "Through Pearson’s correlation coefficient analysis (|R2|> 0.3 and P< 0.05), 206 transcription factors were associated with cancer driver gene expression, and DDX3X, JAK1, EGR2, IKZF3, and CCR7 were the five most enriched cancer driver genes." (PMID 34507558, 2021). "We detected several circRNAs known to be deregulated in other cancers and identified a novel circRNA from the IKZF3 gene." (PMID 30087459, 2018). "Knock-down of the IKAROS family zinc finger 3 (IKZF3), which is part of the VAPB-IKZF3 fusion in BT-474, led to the inhibition of cancer cell growth." (PMID 21247443, 2011). "Data from the DepMap database suggest that IKZF3 and CARM1 are independent dependencies in MM cells and that they are uniquely different from other cancers." (PMID 40123976, 2025). "Here, we describe screening of a library of cereblon (CRBN) ligands against a panel of patient-derived cancer cell lines, leading to the discovery of SJ7095, a potent degrader of CK1α, IKZF1 and IKZF3 proteins." (PMID 38228616, 2024). "Public CRISPR dependency data (depmap.org) identifies IKZF3 and MYC as dependencies in MM cell lines (n = 18), compared to cell lines derived from various other cancers." (PMID 38610997, 2024). "The results confirmed the transcriptional relationship between IKZF1 and IKZF3, because they ranked in the same cluster with a transcriptional pattern similar to that of IKZF1 and IKZF3 in different cancer types." (PMID 36353107, 2022). "With regard to B cells, changes included decreases in the gene expression of CD19, CD22, CD72, IKZF3 and GCSAM in cancer patients compared to healthy donors." (PMID 28936253, 2016). "Screening of our library of CRBN-directed molecular glues against a panel of pediatric cancer cell lines led to the identification of SJ7095 with high cytotoxicity against MOLM-13 cells (IC50 = 71 nM), and potent CRBN-dependent degradation of CK1α, IKZF1 and IKZF3 proteins." (PMID 38228616, 2024).
hematological malignancies (2 papers, 2020). "Degradation of IKZF1 and IKZF3 is therapeutically exploited in the treatment of hematological malignancies." (PMID 32811853, 2020).
infection (2 papers, 2024 to 2025). The state of being infected such as from the introduction of a foreign agent such as serum, vaccine, antigenic substance or organism. "Similarly, the IKZF3 N160S mutation has been shown to affect both B and T cell populations, leading to increased susceptibility to infection." (PMID 39560988, 2024). "To determine whether the increased lung TVM population had trafficked from the spleen or expanded from the lung-resident population, we treated WT and Ikzf3−/− mice with Fingolimod (FTY720) or saline control via the intraperitoneal route daily starting one day prior to PR8 infection." (PMID 40666840, 2025).
hematological cancers (1 paper, 2025). "Elevated expression of Aiolos family zinc finger 3 (IKZF3), a transcription factor crucial for lymphocyte maturation, is observed in hematological cancers." (PMID 40761106, 2025).
IKZF3 also shares sentences with these, for which no sentence is quoted: Allergy (3 papers); B cell lymphoma (3); inflammatory bowel disease (3); non-Hodgkin lymphoma (3); diabetes (2); glomerulonephritis (2); hay fever (2); Pneumocystis jirovecii pneumonia (2); Thrombocytopenia (2); type 1 diabetes (2); type 2 diabetes (2); ulcerative colitis (2); allergic rhinitis (1); atopic dermatitis (1); autoimmune hypothyroidism (1); B cell lymphopenia (1); bladder cancers (1); cardiovascular diseases (1); colon adenocarcinoma (1); colorectal cancer (1); combined immunodeficiency (1); common variable immunodeficiency (1); COVID-19 (1); diabetic neuropathy (1); eczema (1); gastroduodenal ulcer (1); head and neck squamous cell carcinoma (1); infectious disease (1); invasive ductal carcinomas (1); lupus erythematosus (1).
A further 13 diseases each share a sentence with IKZF3 in 1 paper.